ATAD3A (ATPase family AAA domain containing 3A)
Diseases named in the same sentence as ATAD3A in open-access papers (continued):
Sharing a sentence is not in itself a finding about the gene and the disease.
cancer (15 papers, 2011 to 2024). A tumor composed of atypical neoplastic, often pleomorphic cells that invade other tissues. "Continued research on ATAD3A and its regulation will provide valuable insights into the molecular mechanisms underlying cancer progression and the development of effective anti-cancer therapeutics." (PMID 37077859, 2023). "Mutations in ATAD3A can cause mitochondrial disease, and elevated ATAD3A expression in various cancer types is associated with poor patient outcomes." (PMID 37077859, 2023). "Although ATAD3A mutations are rarely found in cancer patients, ATAD3A is still associated with certain types of cancer usually Herald poor patient outcomes." (PMID 38018291, 2023). "Mutations and splice variants in human ATAD3A have also been implicated in numerous genetic disorders, as well as in cancers and neurological syndromes." (PMID 35984838, 2022). "Upregulation of transcription and increased protein stability (post-translation modification) are potential mechanisms for elevated ATAD3A in cancer, as TCGA data analysis indicates that ATAD3A gene amplification and mutation is rare in cancer cells." (PMID 33113782, 2020). "Analysis through the online tool Ubinet® suggests that K358 and K573 are the two putative binding sites for ubiquitin on ATAD3A (isoform 2); however, the underlying mechanisms of ATAD3A expression in cancer remain to be explored." (PMID 33113782, 2020). "Furthermore, ATAD3A has been associated with the sensitivity of the human body to anti-cancer drugs." (PMID 37569886, 2023). "The examination of other relevant cancer tissues also found that the expression level of the ATAD3A gene was significantly increased, and some detected variants, which would have an impact on the physiological activities of cancer cells and the pathological process of cancer." (PMID 38018291, 2023). "Although accumulating evidence indicates that ATAD3A plays a vital role in cancer metastasis, the underlying mechanisms of dissemination related to ATAD3A remain largely unknown." (PMID 33113782, 2020). "According to the experimental result, the expression level of ATAD3A in cancer cells was significantly increased, and the corresponding signal pathway was activated to promote the proliferation of tumor cells." (PMID 38018291, 2023). "Five core genes (ACAT1, PACS2, VDAC1, MFN1, and ATAD3A) playing critical roles in cancer were identified in this study." (PMID 36902617, 2023). "In cancer cell proliferation, the target of ATAD3A regulation is still unclear, and the corresponding regulatory mechanism still needs to be further studied." (PMID 38018291, 2023). "ATAD3A has also been linked to epithelial-mesenchymal transition (EMT), a process by which cancer cells lose their epithelial characteristics and acquire mesenchymal properties, enabling them to invade and migrate." (PMID 37077859, 2023). "In response to ER stress induced by chemotherapy, ATAD3A interacts with the GRP78 protein to mitigate the effects of ER stress on cancer cell survival." (PMID 38018291, 2023). "Nevertheless, developing targeted therapies that specifically inhibit ATAD3A in cancer cells while sparing normal cells will be a challenging but critical task." (PMID 37077859, 2023). "The median expression of ATAD3A in Grade 1 cancer (n = 2) was 20.402, in Grade 2 (n = 129) was 38.115, in Grade 3 (n = 137) was 39.234, and in Grade 4 (n = 132) was 42.653." (PMID 38018291, 2023). "Relevant studies have found that silencing ATAD3A can promote cell death, increase T lymphocyte infiltration, and improve the level of cancer cell apoptosis." (PMID 38018291, 2023). "Silencing of ATAD3A in cancer cell lines led to mitochondrial fragmentation and/or increased chemotherapy drug sensitivity." (PMID 37569886, 2023). "In recent years, a large number of experimental studies have found that the mitochondrial function and biological behavior of cancer cells are mainly related to ATAD3A, thus playing a bridge role." (PMID 38018291, 2023).
cancer (continued). "Not only does ATAD3A promote the resistance of cancer to chemotherapy, but it also negatively affects the therapeutic response of cancer patients to the immune checkpoint inhibitor targeting PD-1/PD-L1 signaling used in combination with chemotherapy." (PMID 37569886, 2023). "There is a strong link between the dysregulation of ATAD3A and diseases such as neurodegenerative disorders and cancer." (PMID 37569886, 2023). "Nevertheless, a comprehensive understanding of the role ATAD3A plays in cancer development needs to be further determined." (PMID 35093151, 2022). "With this information, one of our future research focuses is to understand the clinical significance of ATAD3A in HNSCC patients with tobacco use and explore mechanisms underlying its contribution to smoking-related cancer development." (PMID 35093151, 2022). "Increasing evidence suggests that ATAD3A is engaged in cancer development, progression, and treatment." (PMID 35093151, 2022). "Investigation of ATAD3A expression levels from TCGA Pan-Cancer analysis revealed that ATAD3A was highly expressed in many types of cancer, including HNSCC, which was confirmed by data from the Oncomine database." (PMID 35093151, 2022). "Our data validate that MUC1/ATAD3A/Pink1 axis-mediated mitophagy constitutes a novel mechanism for maintaining the malignancy of cancer cells, providing a novel therapeutic approach for MUC1-positive cancers." (PMID 36289190, 2022). "Herein, we found that ATAD3A overexpression inhibited cancer cell proliferation, tumor-initiating cell self-renewal potential, and tumorigenesis, supporting a tumor suppressor function of ATAD3A." (PMID 36289190, 2022). "ATAD3A is reportedly involved in mitochondrial dynamics, mitochondrial activity, cholesterol metabolism, and cell growth and cancer." (PMID 35582383, 2021). "Considering that the role of ATAD3A in cancer development, progression and treatment outcomes has been experimentally proven, its targeting has emerged as a promising anti-cancer strategy." (PMID 33113782, 2020). "Under hypoxia condition, cancer cells were insensitive to sorafenib treatment, while, gain of ATAD3A expression mitigated the insensitivity as indicated by the fewer colonies and increased apoptotic index in LM3 cells." (PMID 33280610, 2020). "Nevertheless, the potential signaling pathways regulated by ATAD3A in cancer cell proliferation remain poorly understood." (PMID 33113782, 2020). "Increasing evidence has indicated ATAD3A to be essential for cancer cell proliferation and tumor growth." (PMID 33113782, 2020). "Delineating both the biological and pathological roles of ATAD3A will then allow us to shed lights on the steps required to develop more effective anti-ATAD3A approaches for cancer treatment." (PMID 33113782, 2020). "In this review, our current understandings of ATAD3A in cancer development and progression have been outlined." (PMID 33113782, 2020). "It was shown that ATAD3B is expressed in pluripotent embryonic stem cells and in cancer cells where it negatively regulates ATAD3A function." (PMID 31248089, 2019). "Several studies with human cancer cells pointed out a role of ATAD3A and ATAD3B in tumor progression." (PMID 23372768, 2013). "Overexpression of ATAD3A is closely related to cancer patient survival." (PMID 38018291, 2023). "This suggests that the role of ATAD3A varies in different types of cancer." (PMID 37569886, 2023). "The promising nature of the results of this study also suggests that targeting the WA motif of ATAD3A or the ATAD3A-ERK1/2 signaling node may attenuate the oncogenic function of ATAD3A in cancer cells." (PMID 37077859, 2023). "Cancer patients with overexpression ATAD3A have a high recurrence rate." (PMID 38018291, 2023). "Additionally, ATAD3A is crucial for the interaction between mitochondria and the endoplasmic reticulum (ER) in the regulation of ER stress, cholesterol transport, and cancer metastasis." (PMID 37569886, 2023).
cancer (continued). "ATAD3A is one such oncoprotein contributing to mitochondrial dynamics, nucleoid organization, protein translation, cell growth, and cholesterol metabolism, which is understudied in cancers." (PMID 35093151, 2022). "Furthermore, ATAD3A is confirmed as an anti-tumor cytokine involved in sensitivity to chemotherapy and radiation in most cancers." (PMID 35582383, 2021). "Although there have been no or few ATAD3A mutations identified in cancer patients, ATAD3A has nevertheless been implicated in certain types of cancer, where its elevated expression levels have been associated with poor patient outcome." (PMID 33113782, 2020). "Another potential mechanism for increased ATAD3A levels in cancer is an increase in protein stability, which may be regulated by protein kinases." (PMID 33113782, 2020). "In this case, anti-cancer therapies co-targeting ATAD3A and ATAD3B would likely be required, though may give rise to an encouraging synergistic effect leading to greater therapeutic efficacy." (PMID 33113782, 2020). "Indeed, the aberrant activation of ATAD3A in cancer cells drives mitochondrial oncogenic signaling, leading to enhanced tumor-promoting activities." (PMID 33113782, 2020). "Recently, elevated levels of ATAD3A have been reported in several types of cancer and to be tightly correlated with cancer development and progression, including increased cancer cell potential of proliferation, metastasis, and resistance to chemotherapy and radiotherapy." (PMID 33113782, 2020). "This novel molecular reporter endows us to identify novel ATAD3A transcript inhibitors with high confidence, which should interest a range of cancer scientists and clinicians who seek to assess the feasibility of manipulating currently undruggable targets for therapeutic interventions." (PMID 33113782, 2020). "Moreover, it is becoming increasingly clear that ATAD3A maintains grave importance to cancer development, progression, and resistance to chemo and radiotherapy." (PMID 33113782, 2020). "In particular, because the intact portions of the ATPase domain and binding regions are required for ATAD3A function in cancer cells, several approaches have been developed around the inhibition of these portion’s transcription and translation to block ATAD3A’s ATPase activity." (PMID 33113782, 2020). "However, high levels of ATAD3A expression, rather than ATAD3A mutations, have historically been identified in cancer patients." (PMID 33113782, 2020). "In the current review, we reveal ATAD3A as the link between mitochondrial functions and cancer biology and the accumulating evidence presenting ATAD3A as an attractive target for the development of novel cancer therapy to inhibit aberrant cancer metabolism and progression." (PMID 33113782, 2020). "Certain tumor suppressors may also regulate cancer cell growth through interaction with ATAD3A." (PMID 33113782, 2020). "Still, when sorted by statistical significance, ATG4D, ATAD3A, and MRPL41 are found in less apical positions in the lists of the top 200 genes negatively correlated with GALC expression in the other human cancer data sets investigated here." (PMID 38474307, 2024). "ATAD3A and GRP78 together stabilize WASF3 at the mitochondrial membrane, promoting cancer metastasis." (PMID 37569886, 2023). "In one study, ATAD3A phosphorylation by PKC, a prototypical class of serine/threonine kinases participating in cancer progression, was confirmed." (PMID 33113782, 2020). "Since ATAD3A-mediated ERK1/2 phosphorylation is RAS-independent, it will be important to harness this signaling pathway along with the cytoplasmic ERK1/2 cascade to develop more effective anti-cancer therapies." (PMID 37077859, 2023). "ATAD3A is ubiquitously expressed in all tissues from very early embryonic stages to adulthood, while ATAD3B is specifically expressed in human embryonic stem cells and is re-expressed in certain types of cancers." (PMID 35093151, 2022).
cancer (continued). "Although there are no or few ATAD3A mutants reported in human cancers, the overexpression of ATAD3A has been observed in a high percentage of primary HNSCC tumors, including those HNSCC patients with the worst prognosis." (PMID 35093151, 2022). "Co-inhibition of ATAD3A and RAS pathways may have a better therapeutic potential for cancer treatment." (PMID 35093151, 2022). "As ATAD3A-mediated ERK1/2 phosphorylation is RAS-independent, it will be essential to harness this signaling together with the cytoplasmic ERK1/2 cascade to develop more effective regimens for combating cancer." (PMID 35093151, 2022). "The exact mechanisms by which ATAD3A promotes cancer metastasis are not fully understood, but it is thought to be related to its regulation of mitochondrial metabolism and dynamics, as well as its interaction with WASF3-dependent metastatic cascade involved in cancer progression." (PMID 37077859, 2023). "Similarly, there is no consensus about the role of ATAD3A in cancer." (PMID 36289190, 2022).
tumor (15 papers, 2013 to 2024). "In prostate cancer, loss of ATAD3A reduces the secretion of prostate-specific antigen and resensitizes cisplatin-resistant tumor cells to cisplatin." (PMID 35093151, 2022). "Paclitaxel upregulates ATAD3A to suppress mitophagy-mediated recruitment and subsequent degradation of PD-L1 protein, resulting in its excessive accumulation on cell membrane to markedly enhance tumor-induced immune deficiency." (PMID 36627348, 2023). "Loss of ATAD3A increased HCC tumor growth in the presence of sorafenib treatment." (PMID 33280610, 2020). "Moreover, salirasib was effective in inhibiting tumor cell proliferation in mice and synergized with ATAD3A loss in hampering tumor growth, as illustrated by the lowest number of Ki67-positive cells in xenograft tumors derived from mice receiving salirasib treatment and ATAD3A gene depletion." (PMID 35093151, 2022). "A blocking peptide, TAT‐PEP, specifically abrogating ATAD3A phosphorylation, results in elevated cell death by preventing doxorubicin‐induced senescence, thus leading to enhanced tumor sensitivity to chemotherapy." (PMID 39520088, 2024). "Higher expression of ATAD3A related to age (p = 0.029), tumor size (p = 0.001), tumor number (p = 0.039), lymph node metastasis (p = 0.001), distant metastasis (p = 0.039), lymphatic invasion (p = 0.040), and TNM stage (p = 0.017)." (PMID 38018291, 2023). "High expression of ATAD3A was correlated with patient age, tumor size, number of tumors, distant metastasis, lymph node metastasis, lymphovascular invasion, and TNM stage (p < 0.05)." (PMID 38018291, 2023). "Next, it is very needed to research the relation between ATAD3A and tumor progression, clinicopathological features, and overall survival." (PMID 38018291, 2023). "Mechanistically, the tumor suppression induced by overexpression of the Walker A dead mutant of ATAD3A (K358) produces a potent dominant-negative effect due to defective ATP binding." (PMID 37077859, 2023). "Loss of ATAD3A expression suppresses HNSCC cell growth and induces tumor regression in orthotopic tumor-bearing mice, whereas gain of ATAD3A expression has the opposite effect." (PMID 37077859, 2023). "Most importantly, the ATAD3A-ERK1/2 signaling axis drives HNSCC development in a RAS-independent manner, and thus tumor suppression is more effective when ATAD3A knockout is combined with RAS inhibitor treatment." (PMID 37077859, 2023). "Further investigations of the role of Atad3a-Pink1-mitophagy axis in regulating in vivo antitumor immunity showed that simultaneous knockdown of Pink1 reversed the effect of Atad3a knockdown on tumor growth." (PMID 36627348, 2023). "This research result has given strong evidence that ATAD3A contributes to tumor development and spread." (PMID 38018291, 2023). "From a mechanistic perspective, the tumor suppression induced by the overexpression of the Walker A dead mutant of ATAD3A (K358) produces a potent dominant-negative effect due to defective ATP-binding." (PMID 35093151, 2022). "Three weeks after inoculation, the tumor size in the mice receiving ATAD3A KO cells was significantly smaller compared with that in mice receiving the parental cells, as measured by bioluminescence and tumor volume." (PMID 35093151, 2022). "A marked increase in tumor growth was observed in mice that were implanted with ATAD3A-overexpressing HN12 cells compared with mice receiving parental cells." (PMID 35093151, 2022). "In line with in vitro data, either KO of ATAD3A or overexpression of its WA dead mutant significantly suppressed tumor outgrowth in mice, as evidenced by reduced bioluminescence intensity and tumor size compared with the other two groups." (PMID 35093151, 2022). "In lung adenocarcinoma, ATAD3A overexpression correlates with tumor stage and lymphovascular involvement in patients, and silencing its expression increases mitochondrial fragmentation and cisplatin sensitivity." (PMID 35093151, 2022).